AFP (alpha fetoprotein)
Diseases named in the same sentence as AFP in open-access papers (continued):
Sharing a sentence is not in itself a finding about the gene and the disease.
Stillbirth (5 papers, 2008 to 2025). Death of the fetus in utero after at least 22 weeks of gestation. "Low maternal serum second trimester levels of estriol and high levels of AFP, hCG and inhibin are all associated with an increased risk of later stillbirth but a meta-analysis indicated that the associations were generally weak." (PMID 40497429, 2025). "Adding measurement of AFP and hCG to maternal characteristics had a minimal effect on prediction of stillbirth risk at term but had a much greater effect on the prediction of stillbirth risk at preterm gestational ages." (PMID 40497429, 2025). "We have previously reported the association between circulating concentrations of alpha fetoprotein and human chorionic gonadotrophin in maternal blood at 15–20 weeks gestation and the risk of stillbirth." (PMID 19019223, 2008).
testicular seminoma (5 papers, 2016 to 2025). A malignant germ cell tumor arising from the testis. "Postoperative pathology confirmed testicular seminoma, with immunohistochemical staining demonstrating the following profile: alpha-fetoprotein (AFP) (−), CD117 (focal positivity, 9.7%), CK-P (−), Ki-67 (70% positive), and Inhibin-α (−)." (PMID 40492123, 2025). "Pre-operative labs were significant for an elevated serum AFP, inconsistent with the diagnosis of testicular seminoma." (PMID 37485120, 2023). "Another case report describes a similar case of a patient with a histologic diagnosis of a testicular seminoma who had elevated serum AFP, which was treated similarly with BEP chemotherapy." (PMID 37485120, 2023). "We report a case of pure testicular seminoma at orchiectomy with elevated serum AFP and DUPAN-2 presenting retroperitoneal metastasis." (PMID 27150447, 2016). "We report a case of pure testicular seminoma with elevated serum alpha-fetoprotein and DUPAN-2 presenting retroperitoneal metastasis." (PMID 27150447, 2016). "In conclusion, here we report a case of pure testicular seminoma with elevated serum AFP and DUPAN-2 presenting retroperitoneal metastasis." (PMID 27150447, 2016). "Elevated LDH and bHCG, along with normal AFP, are typical findings in testicular seminoma." (PMID 40166779, 2025). "We describe a case of nonpalpable pure testicular seminoma with elevated serum alpha-fetoprotein presenting retroperitoneal metastasis." (PMID 27150447, 2016).
thyroid cancer (5 papers, 2020 to 2023). "High ratios of overlap were identified for skeletal muscle mass (95%) and alkaline phosphatase (93.48%), and low ratios for thyroid cancer (0%) and alpha fetoprotein (8%)." (PMID 35121771, 2022). "A search of COSMIC showed that AFP mutations are present in numerous cancers, including thyroid cancer, even though they have not been thoroughly investigated." (PMID 36941725, 2023).
colitis (4 papers, 2022 to 2025). Inflammation of the colon. "IL-1β and IL-6 serum levels were significantly higher in the model and CDP groups, while CEA and AFP levels exhibited similar trends, indicating that CDPs facilitate the development of internal tumors in colitis mice models." (PMID 40911847, 2025).
cryptorchidism (4 papers, 2014 to 2024). The failure of one or both testes of a male fetus to descend from the abdomen into the scrotum during the late part of pregnancy. "In one study, high AFP levels and low birth weight were both associated with cryptorchidism." (PMID 25064170, 2014). "This study showed a link between low maternal serum hCG levels and cryptorchidism in boys from uncomplicated pregnancy, while normal AFP levels indicated a normal fetoplacental unit." (PMID 25064170, 2014).
endometrial carcinoma (4 papers, 2015 to 2024). A malignant tumor arising from the epithelium that lines the cavity of the uterine body. "Proposed essential and desirable diagnostic criteria for AFP-producing endometrial carcinomas." (PMID 34977100, 2021). "The clinicopathological, immunohistochemical, and molecular characteristics of α-fetoprotein (AFP)-producing endometrial carcinoma (AFP+ EC) are poorly understood." (PMID 34977100, 2021). "From 284 cases of endometrial carcinoma that had undergone hysterectomy at Kindai University Hospital between January 2015 and December 2020, five cases of AFP+ ECs were identified." (PMID 34977100, 2021). "Once the existence of endometrial carcinoma with AFP production is widely recognized, this highly malignant tumor will be more frequently diagnosed appropriately." (PMID 34977100, 2021). "From 284 cases of endometrial carcinoma in our pathology archive, we identified five cases (1.8%) of AFP+ EC with fetal gut–like (4/5) and/or hepatoid (2/5) morphology." (PMID 34977100, 2021). "Immunohistochemical characteristics of AFP-producing endometrial carcinoma and other endometrial neoplasms in differential diagnosis." (PMID 34977100, 2021). "In conclusion, we revealed that AFP+ EC is a clinicopathologically distinct subtype of endometrial carcinoma, occurring in 1.8% of endometrial carcinoma cases." (PMID 34977100, 2021). "In conclusion, the NINJ2 gene polymorphism loci rs118050317 mutant allele C was associated with an increased risk of endometrial cancer and there was significant higher quantity in serum of CEA, CA125 and AFP in cases than controls." (PMID 33397383, 2021). "Immunohistochemical and molecular analysis of AFP-producing endometrial carcinoma." (PMID 34977100, 2021). "In addition, 24 cases of endometrial carcinoma with elevated serum AFP levels were retrieved from the literature." (PMID 34977100, 2021). "Clinicopathological characteristics of AFP-producing endometrial carcinoma." (PMID 34977100, 2021). "CEA, CA125 and AFP quantities were significant higher in endometrial cancer patients." (PMID 33397383, 2021). "Isolated expression of one of these markers, such as SALL4, Glypican-3, and AFP is not uncommon in endometrial carcinoma without yolk sac differentiation." (PMID 39408649, 2024).
fibrolamellar carcinoma (4 papers, 2015 to 2022). "Alpha-fetoprotein levels are normal in the majority of patients with fibrolamellar carcinoma, a variant of HCC." (PMID 29201680, 2015).
gestational diabetes (4 papers, 2020 to 2025). Carbohydrate intolerance first diagnosed during pregnancy. "It measures dimeric inhibin A, alpha-fetoprotein (AFP), hCG, and unconjugated estriol while considering the patient’s age, race, weight, gestational age, gestational diabetes status, and the number of fetuses." (PMID 40282900, 2025).
hemochromatosis (4 papers, 2022 to 2025). A disorder of iron metabolism characterized by a triad of HEMOSIDEROSIS; LIVER CIRRHOSIS; and DIABETES MELLITUS. "The benefits of measuring alpha-fetoprotein concentration in addition to ultrasound remains unclear across a range of liver diseases, including hemochromatosis." (PMID 37067673, 2023). "In patients with cirrhosis due to hemochromatosis, six-monthly surveillance with ultrasound, with or without alpha-fetoprotein testing is recommended." (PMID 37067673, 2023).
hypercalcaemia (4 papers, 2004 to 2021). "After 3 doses, despite an improvement in liver function tests and AFP, the patient developed abdominal pain, delirium, significant asthenia and uncontrolled hypercalcaemia." (PMID 23426888, 2013). "After 2 months of treatment, control of hypercalcaemia was achieved, with a drop in AFP levels." (PMID 23426888, 2013).
hypersplenism (4 papers, 2014 to 2024). Overactive functioning of the spleen, resulting in excessive destruction of blood cells. "Tumor size, high AFP level and hypersplenism were independent risk factors of MVI for patients with solitary small HCC." (PMID 24772137, 2014). "Risk factors of microvascular invasion: In the univariate analyses, tumor size, positive HBV-DNA level, preoperative AFP level greater than 400 ng/mL and hypersplenism were potential risk factors for MVI (Table-I)." (PMID 24772137, 2014). "Using tdROC curves, the predictive value of the new scoring model for the incidence of MVI was compared to the predictive value based on tumor number ≥3, tumor size ≥5 cm, AFP ≥1000 ng/mL, hypersplenism, and ascites." (PMID 30544459, 2018). "However, in the multivariate study, only tumor size, preoperative AFP level greater than 400 ng/mL and hypersplenism were independent predictors for MVI (Table-II)." (PMID 24772137, 2014).
mucinous adenocarcinoma (4 papers, 2018 to 2025). An invasive adenocarcinoma composed of malignant glandular cells which contain intracytoplasmic mucin. "In a case review of 27 EOC patient samples, EOC-producing AFP was identified in three patients, with particularly high AFP levels observed in specific subtypes, such as clear cell and mucinous carcinoma." (PMID 40430002, 2025).
neuroblastoma (4 papers, 2013 to 2025). Neuroblastoma (NB) is the most common solid, extracranial childhood tumor. "In some cases with calcifications in the mass, the differentials are further converged to sacrococcygeal teratoma and rarely presacral neuroblastoma.[4.5] Problem arises when AFP is inconclusive of SCT." (PMID 26023495, 2014).
ovarian adenocarcinoma (4 papers, 1981 to 2022). An adenocarcinoma that arises from the ovary. "Various other serum tumor markers (including AFP and CA-125) facilitate the differential diagnosis of ovarian adenocarcinoma." (PMID 25120684, 2014). "In this study the incidence of CEA, AFP, and hCG (beta subunit) were studied in patients with adenocarcinoma of the ovary, adenocarcinoma of the cervix, and squamous-cell carcinoma of the cervix." (PMID 6169360, 1981). "Experiments with radioactively labeled an AIF (AFP-3BC) have confirmed that they selectively accumulate in cancer cells and that AFP-3BC loaded with drugs binds to human breast MCF7 cells and ovarian adenocarcinoma SKOV3 cells, suppressing the proliferation of these cancer cells." (PMID 33898423, 2021).
progressive ataxia (4 papers, 2013 to 2023). "We selected 22 Italian patients from 21 families, presenting progressive cerebellar ataxia, axonal neuropathy, and elevated serum AFP." (PMID 23941260, 2013). "Because of his rarity, the diagnosis of AT is often delayed but it can be made earlier with serum alpha feto-protein (AFP) measurement, a readily available and inexpensive test for all toddlers and children with undiagnosed chronic or progressive ataxia." (PMID 30016966, 2018).
rectal cancer (4 papers, 2015 to 2025). A primary or metastatic malignant neoplasm that affects the rectum. "The outcomes of preoperative chemoradiotherapy against AFP-producing rectal cancer are reported here for the first time." (PMID 30191347, 2018). "We report a case of a patient with AFP-producing rectal cancer which successfully responded to preoperative chemoradiotherapy." (PMID 30191347, 2018). "The effectiveness of preoperative chemoradiotherapy for AFP-producing rectal cancer is reported here for the first time." (PMID 30191347, 2018). "In our patient, AFP-producing rectal cancer responded to preoperative chemoradiotherapy, and R0 resection was achieved." (PMID 30191347, 2018). "Based on our experience with this patient, it appears preoperative chemoradiotherapy for patients with AFP-producing advanced rectal cancer is feasible." (PMID 30191347, 2018). "Here, we report a case with early rectal cancer diagnosed as an AFP-producing tumor by immunohistochemistry." (PMID 25962419, 2015). "Although there are several reports of an AFP-GC with features of hepatic differentiation, the mechanisms of AFP-producing rectal cancer or the hepatic differentiation remain obscure." (PMID 25962419, 2015). "Alpha-fetoprotein (AFP)-producing rectal cancer is very rare, and this type of cancer frequently metastasizes to the liver with a poor prognosis." (PMID 25962419, 2015). "We report on a patient with AFP-producing rectal cancer diagnosed at an early stage." (PMID 25962419, 2015).
teratocarcinoma (4 papers, 2013 to 2021). A germ cell tumor characterized by the presence of an embryonal carcinoma component and a teratoma component. "On the other hand, AFP-positive staining patterns of teratocarcinoma and immature glandular components were similar between Parg−/− and wild-type tumors." (PMID 32344695, 2020).
Thrombocytosis (4 papers, 2020 to 2026). Increased numbers of platelets in the peripheral blood. "Laboratory analysis usually reveals elevated alpha-fetoprotein (AFP) levels associated with thrombocytosis, often without changes in liver enzymes." (PMID 41008814, 2025).
urothelial carcinoma (4 papers, 2022 to 2025). A malignant neoplasm derived from the transitional epithelium of the urinary tract (urinary bladder, ureter, urethra, or renal pelvis). "Serum AFP fluctuation can be used for monitoring the disease course, risk evaluation, and treatment response and can determine clinical outcomes in patients with GC, urothelial carcinoma, childhood NSGCTs, neonatal SCT, NUT midline carcinoma, and APOs." (PMID 37781207, 2023). "Most of these tumors present hepatoid tissue areas in the context of adenocarcinoma or urothelial carcinoma and show AFP positivity." (PMID 35027045, 2022). "AFP-producing urothelial carcinoma is rarely reported in the literature." (PMID 40406259, 2025).
Wilms tumor (4 papers, 2021 to 2025). An embryonal neoplasm characterized by the presence of epithelial, mesenchymal, and blastema components. "However, AFP is not produced in the kidneys during prenatal or childhood stages, and thus AFP has never been a marker for Wilms tumor." (PMID 37686577, 2023).
angiosarcoma (3 papers, 2015 to 2021). A malignant tumor arising from the endothelial cells of the blood vessels. "AFP is not elevated within most of the reported angiosarcomas." (PMID 27684838, 2016).
Beckwith-Wiedemann syndrome (3 papers, 2019 to 2025). Beckwith-Wiedemann syndrome (BWS) is a genetic disorder characterized by overgrowth, tumor predisposition and congenital malformations. "For certain risk groups for early HB diagnosis (e.g. Beckwith-Wiedemann syndrome or Simpson-Golabi Behmel) abdominal ultrasounds and AFP screenings every 3 months have been recommended, starting from birth." (PMID 40504251, 2025).
bladder cancer (3 papers, 2010 to 2025). "As a result, we presume that the elevated serum AFP was produced by the bladder cancer tissue." (PMID 40406259, 2025). "Iles and associates measured human chorionic gonadotrophin (hCG) and alpha-feto-protein (AFP) in culture media from a panel of 29 cell lines including 9 bladder carcinomas, 5 'normal' bladder epithelia, 10 germ cell tumours, and 5 miscellaneous tumours and 'normal' cell lines." (PMID 21918707, 2010). "Serum AFP testing is not routinely performed in patients with bladder cancer." (PMID 40406259, 2025).
bowel cancer (3 papers, 2021 to 2024). "Increased alpha-fetoprotein levels can also indicate other cancers, including testicular, stomach, and bowel cancer." (PMID 38463849, 2024). "Therefore, some authors suggest that, on the one hand, bowel cancer patients should undergo routine preoperative screening for AFP to assist in diagnosis." (PMID 37950062, 2023).
cerebrovascular disease (3 papers, 2023 to 2025). "Univariate analysis showed that BCLC stage C, portal vein tumor thrombus, cerebrovascular disease, surgical treatment, AFP ≥ 400 ng/mL, and high AST levels were associated with shorter OS." (PMID 40356761, 2025).
Epithelial ovarian tumors (3 papers, 2013 to 2025). "The tumor does not produce hCG or AFP and usually has normal or lower CA125 levels compared to those seen in association with more common epithelial ovarian tumors." (PMID 23856407, 2013).
gastroschisis (3 papers, 2021 to 2024). Gastroschisis is marked by viscera protruding, without a covering sac, from the fetal abdomen on the right lateral base of the umbilicus. "Antenatal ultrasound scans can often diagnose gastroschisis as early as 12 weeks gestation, along with elevated levels of maternal serum alpha-fetoprotein." (PMID 39311328, 2024).
glioma (3 papers, 2013 to 2025). A benign or malignant brain and spinal cord tumor that arises from glial cells (astrocytes, oligodendrocytes, ependymal cells). "IFNAR2 and PARP9 show differences across all groups, while AFP and GFRA1 are significantly differentially expressed only between other gliomas and GBM." (PMID 36834486, 2023). "Expressions of candidates such as AFP, DLL1, and GRB14 were non-significant compared to normal samples; however, they were highly significant across different gliomas." (PMID 36834486, 2023).
hydatidiform mole (3 papers, 2013 to 2023). A gestational trophoblastic disorder characterized by marked enlargement of the chorionic villi, hyperplasia of the villous trophoblastic cells and hydropic changes. "In all cases, alpha-fetoprotein was elevated, unlike normal or hydatidiform mole pregnancies." (PMID 35204384, 2022).
hypothyroidism (3 papers, 2018 to 2023). Abnormally low levels of thyroid hormone. "The patient achieved a recurrence-free survival time of 24 months, but he experienced elevated alpha fetoprotein, Grade 2 hypothyroidism and pruritus while on adjuvant therapy." (PMID 37965538, 2023). "Several predictors for the efficacy of lenvatinib (4-week relative dose intensity, AFP, ALBI grade, neutrophil-to-lymphocyte ratio, and occurrence of hypothyroidism) have been reported previously." (PMID 35053484, 2022).
infantile hemangioma (3 papers, 2016 to 2024). "The embryonic-like stem cell origin of infantile hemangioma (IH) and the observed elevated serum levels of alpha-fetoprotein (AFP) in patients with hepatic IH led us to investigate if this tumor was the source of AFP." (PMID 26904545, 2016). "Functional analysis of serial serum levels of AFP in children with infantile hemangioma and normal American and Japanese children." (PMID 26904545, 2016).
Infertility (3 papers, 2014 to 2024). "AFP is critical for the proper development of gonadal tissue; therefore, lack of AFP might partially be the cause of infertility observed in SH3PXD2b -mutant mice and FTHS-affected individuals." (PMID 35955935, 2022). "According to guidelines, small testicular lesion (tumor volume <2.8 cm3) with history of hormone disorders (AFP, HCG and LDH) or infertility and long duration of symptoms predict benign histology and testis-sparing surgery (TSS) is recommend." (PMID 39467414, 2024).
macrosomia (3 papers, 2021 to 2025). "Notably, both elevated and reduced AFP concentrations are associated with abnormal fetal growth: higher AFP levels correlate with an increased risk of FGR or LBW newborns, while lower levels are linked to LGA infants or macrosomia." (PMID 41034923, 2025).